GRM8 (glutamate metabotropic receptor 8)
Diseases named in the same sentence as GRM8 in open-access papers (continued):
Sharing a sentence is not in itself a finding about the gene and the disease.
pituitary adenomas (1 paper, 2020). "Druggable genes shared by all types of pituitary adenomas included NRG1, KCNA4, NCAM1, GRIA2 and GRM8." (PMID 33168897, 2020).
prion disease (1 paper, 2024). A transmissible disease that is caused by a protein that is able to induce abnormal folding of normal cellular proteins, leading to characteristic spongiform brain changes, which are associated with neuronal loss without an inflammatory response. "For instance, the metabotropic glutamate receptors Grm5 and Grm8 mediate prion toxicity, while Bmerb147, Macrod246, and Stmn248 are implicated as putative genetic risk loci for prion disease." (PMID 39580485, 2024).
Rubinstein-Taybi syndrome (1 paper, 2016). A rare malformation syndrome characterized by congenital anomalies (microcephaly, specific facial characteristics, broad thumbs and halluces and postnatal growth retardation), short stature, intellectual disability and behavioral characteristics. "These include single-gene exonic deletions in NRXN1, GRM8, CREBBP (Rubinstein-Taybi syndrome, MIM:180849), KDM4B, and DMD." (PMID 27257017, 2016).
Squamous non-small cell lung cancer (1 paper, 2021). "Squamous non-small cell lung cancer (NSCLC), adenocarcinomas, and melanomas have all been linked to mutations in the glutamate receptors GRM8, GRM1, and GRM3." (PMID 34943797, 2021).
tauopathy (1 paper, 2024). Neurodegenerative disorders involving deposition of abnormal tau protein isoforms (tau proteins) in neurons and glial cells in the brain. "Through comparison of multiple transcriptome datasets, followed by gene ontology analysis and protein–protein interaction mapping, we identified GRIN3A and GRM8 as the top two genes related to loss of postsynaptic function and tauopathy." (PMID 39396906, 2024). "Interestingly, we identified that decreased NR3A (encoded by GRIN3A) and mGluR8 (encoded by GRM8) are correlated with tauopathy and loss of postsynaptic function in AD." (PMID 39396906, 2024).
Tics (1 paper, 2017). Repeated, individually recognizable, intermittent movements or movement fragments that are almost always briefly suppressible and are usually associated with awareness of an urge to perform the movement. "One of these findings is the 258 kb duplication encompassing the gene GRM8, coding for a glutamate receptor, in 7q31.33, paternally inherited, observed in a female patient with EO-OCD and comorbid tics, but not in her sister with EO-OCD." (PMID 29179725, 2017).
tumor (11 papers, 2020 to 2025). "This specific expression suggests that GRM8 can be targeted, while the enrichment in loss-of-function mutations suggests that the activity of GRM8 is detrimental to SCLC tumours." (PMID 40931078, 2025). "Consequently, targeting GRM8 and similar regulatory genes may represent a viable strategy for reactivating sensitivity to the tumor‐suppressive and pro‐senescent effects of the TGF‐β/Smad3 axis." (PMID 40083231, 2025). "In addition, GRM8 upregulation rescued miR-33a-5p-mediated tumor growth inhibition in vivo." (PMID 34950209, 2021). "In our datasets, GRM8 showed expression specifically in SCLC and a few other tumour types, a statistically significant enrichment of both non-synonymous mutations and more severe loss-of-function mutations, and a significant number of piggyBac insertions." (PMID 40931078, 2025). "The expression of mGluR1 (GRM1) and mGluR5 (GRM5) was conserved from primary tumours to metastatic samples, but moderate changes were evident for other receptors such as mGluR2/3/7/8 (GRM2, GRM3, GRM7, and GRM8)." (PMID 37173906, 2023).
cancer (8 papers, 2016 to 2025). A tumor composed of atypical neoplastic, often pleomorphic cells that invade other tissues. "Metabotropic glutamate receptor 8 (GRM8) is a G-protein-coupled receptor and mutations in GRM8 are observed in human cancers." (PMID 26894861, 2016). "Similarly, GRM8, a metabotropic glutamate receptor, is a G‐protein coupled receptor implicated in various cancers." (PMID 40083231, 2025). "Several studies have reported that GRM8 is closely implicated in several kinds of cancers." (PMID 34950209, 2021). "GPCRs are considered viable therapeutic targets in cancer treatment, and GRM8 is no exception." (PMID 40083231, 2025). "In addition to the C3, for these genes (CXCL8, CX3CR1, GRM8, HTR1B, HTR1D, PTGER3, SSTR1 and SUCNR1) were related to survival in the ACC and it was also could be useful in other cancers 24-31." (PMID 34220331, 2021).
psychiatric disorder (4 papers, 2017 to 2022). A disorder characterized by behavioral and/or psychological abnormalities, often accompanied by physical symptoms. "Taken together, the two here newly developed animal models of Grm8 loss-of-function may be useful for the investigation of the mechanistic backgrounds of behavioral phenotypes with relevance to psychiatric disorders." (PMID 35769333, 2022). "The current knowledge about Grm8 function in psychiatric disorders is scarce because the field lacks validated models in different species to address open questions." (PMID 35769333, 2022).
neurological diseases (2 papers, 2021 to 2024). "This commends GRM8 activation as a valuable therapeutic approach to counteract inflammation-driven neurodegeneration in MS and other neurological diseases that involve glutamate excitotoxicity." (PMID 33661276, 2021).
kidney disorder (1 paper, 2023). A disease involving the kidney. "In this work, we discovered 20 top eccDNA hub genes in which NCAM1, NFATC1, PRKCB, LEF1, PRKAG2, and GRM8 were strongly linked to a variety of kidney disorders." (PMID 36967395, 2023).
GRM8 also shares sentences with these, for which no sentence is quoted: glioma (4 papers); glioblastoma (2); lung adenocarcinoma (2); adenocarcinoma (1); amyloid (1); amyotrophic lateral sclerosis (1); anxiety disorder (1); astrocytoma (1); attention deficit-hyperactivity disorder (1); blastoma (1); brain injury (1); cardiac arrhythmia (1); cognitive decline (1); colorectal cancer (1); ependymoma (1); Hearing impairment (1); hepatocellular carcinoma (1); Hydrocephalus (1); melanoma (1); metastatic colorectal cancer (1); mood disorder (1); multiple sclerosis (1); neurodevelopmental disorder (1); neuronal tumor (1); neuropathic pain (1); ovarian carcinoma (1); Parkinson disease (1); psychosis (1); spinal cord contusion (1); virus infection (1).